LRP1 (LDL receptor related protein 1)
Diseases named in the same sentence as LRP1 in open-access papers (continued):
Sharing a sentence is not in itself a finding about the gene and the disease.
Stroke (22 papers, 2013 to 2026). Sudden impairment of blood flow to a part of the brain due to occlusion or rupture of an artery to the brain. "In the stroke mouse model, Lrp1 knockdown mice exhibited larger infarct areas and worse neurological function." (PMID 40984037, 2025). "In stroke patients, high cerebrospinal fluid lactate levels correlate with astrocyte mitochondrial damage, highlighting the protective role of LRP1 in stroke through astrocyte-neuron crosstalk." (PMID 40536597, 2025). "The strong link between LRP1 and stroke via the atherosclerotic pathway renders LRP1 as a potential therapeutic target for stroke in this population." (PMID 38550935, 2023). "Aside from the benefits regarding our understanding of post-stroke migration to lesions, the implications of LRP1 regulation of CXCR4 are broad, as CXCR4 plays a vital role in multiple neurogenic and stem cell processes." (PMID 37186298, 2023). "Further, the commercially available inhibitor of LRP-1 was also available, which was previously used clinically in the patient with stroke." (PMID 36267880, 2022). "Modest elevations were observed in LOPC 8 h exposed animals over stroke alone in mRNA expression of LRP-1 and RAGE products." (PMID 33841293, 2021). "In this study, we assessed the neuroprotective potential of carnosine encapsulated in polymersomes with Angiopep-2 for LRP-1-mediated targeted delivery to the CNS in experimental stroke." (PMID 31959846, 2020). "LRP1 is expressed on neurons, microglia, and perivascular astrocytes and interaction of tPA with LRP1 is detrimental in stroke." (PMID 23658802, 2013). "RAP is a potent inhibitor of LRP‐1, but strong, non‐selective inhibition of LRP‐1 may have varying effects on stroke and tPA‐induced HT." (PMID 40116141, 2025). "We sought to test a role for LRP1 in regulation of NSCs in the post-stroke milieu." (PMID 37186298, 2023). "In a case-control study of the Ischemic Stroke Genetics Study (ISGS) cohort, the LRP1 rs11172113 variant was associated with stroke among African Americans without a replication of that association in the non-Hispanic White cohort." (PMID 34828431, 2021). "Based on this study’s results, sLRP1 and LRP1 play a key role in neuroinflammation by regulating cytokine expression and cell signaling in microglia, implicating sLRP1 in many disease processes in which microglia release pro-inflammatory mediators, including stroke." (PMID 33498620, 2021). "In summary, inhibiting LRP1 induced ARF1‐K73la can promote mitochondrial transport and improve stroke prognosis." (PMID 40984037, 2025). "Notably, LRP1 can regulate the endocytic clearance of several MMPs, which could degrade the extracellular matrix to promote VSMC migration and thin the fibrous cap, causing plaque rupture and leading to myocardial infarction and stroke." (PMID 34124208, 2021). "LOPC 8 h modestly elevated LRP1 and RAGE mRNA levels (p < 0.001 and p < 0.05, respectively), and LOPC 24 h increased ECE mRNA levels (p < 0.001), relative to stroke only animals." (PMID 33841293, 2021). "Recent research suggests stroke-triggered reactive astrocytes overexpress lipocalin 2 (LCN2), binding to low-density lipoprotein receptor-related protein 1 (LRP1), activating phagocytosis and inducing astrocytes to phagocytose myelin fragments, causing demyelinating lesions." (PMID 37720543, 2023). "By competing with membrane-bound LRP1 for its ligands, sLRP1 potentially plays an important role in heme scavenging, BBB permeability, and inflammation and pathophysiological processes that are important in stroke." (PMID 33498620, 2021).
melanoma (20 papers, 2013 to 2023). A malignant, usually aggressive tumor composed of atypical, neoplastic melanocytes. "The multifunctional endocytic receptor low-density lipoprotein receptor-related protein 1 (LRP1) has been implicated in melanoma growth." (PMID 36612285, 2022). "Therefore, LRP1 may be a potentially feasible protein to therapeutically target in the treatment of melanoma with mutated YAP." (PMID 29138479, 2017). "Earlier studies demonstrated that ApoE and tPA binding to LRP1 drives melanoma cell proliferation and metastasis." (PMID 36612285, 2022). "Consistent with the role of LRP1 in melanoma cell growth, we found that LRP1 OE enhanced melanoma cell growth." (PMID 36612285, 2022). "We found that the apoptosis-inducing effects of YO-2 were mediated through LRP1 as restoration of LRP1 rendered melanoma cells YO-2 resistant." (PMID 36612285, 2022). "Herein, we studied the molecular mechanism of LRP1 downregulation by YO-2 that induces apoptosis in melanoma cells." (PMID 36612285, 2022). "APOE is secreted by melanoma cells and targets the low density lipoprotein receptor-related protein 1 (LRP1) receptor on other melanoma cells and the LRP8 receptor on endothelial cells, leading to the inhibition of migration of melanoma cells." (PMID 35884446, 2022). "LRP1 augments melanoma growth and metastasis by binding to the fibrinolytic factor tissue-type plasminogen activator (tPA)." (PMID 36612285, 2022). "We observed that the small-molecule plasmin inhibitor YO-2 downregulates LRP1 expression and suppresses melanoma growth." (PMID 36612285, 2022). "We recently showed that the chemotherapeutic drug bortozomib induced the expression of LRP1 and its ligand tPA in melanoma cells." (PMID 33669052, 2021). "In murine models of melanoma, ApoE secreted by melanoma cancer cells suppressed tumor invasion and metastatic endothelial cell recruitment by binding to LRP1-positive melanoma cells and LRP8-positive endothelial cells." (PMID 33669052, 2021). "When LRP1 and tPA were restored in less aggressive, poorly metastatic melanoma cells, melanoma cell growth and lung metastasis were accelerated." (PMID 33669052, 2021). "Their results, using loss- and gain-of-function strategy demonstrated a model wherein LRP-1 drives melanoma growth and metastases by enhancing ERK activation resulting in increased proteolytic events and in changing the cellular content within the tumor." (PMID 32582700, 2020). "Salama and collaborators reported the involvement of LRP-1:tPA pathway in promoting melanoma cell migration and proliferation." (PMID 32582700, 2020). "We discovered that luciferase activity of the LRP1 promoter was largely enhanced by transfecting the YAP-FLAG plasmid into melanoma A375 cells and MUM-2B cells." (PMID 29138479, 2017). "We also transfected YAP-FLAG and LRP1-FLAG into melanoma A375 cells and MUM-2B cells, and the results showed that both promoted transformative phenotypes of A375 cells and MUM-2B cells." (PMID 29138479, 2017).
melanoma (continued). "Activity of the LRP1 promoter was inhibited by transfecting the YAP-sh plasmid into melanoma A375 cells and MUM-2B cells, when compared to those infected by the GFP-sh plasmid." (PMID 29138479, 2017). "It was further indicated that the expression of YAP was closely correlated with the expression of LRP1 in melanoma skin tissues." (PMID 29138479, 2017). "In this experiment, we have found a relationship between YAP and LRP1 in the tumorigenesis of melanoma." (PMID 29138479, 2017). "In the previous experiments, we revealed that YAP and LRP1 play similar roles in maintaining transformative phenotypes in melanoma A375 cells and MUM-2B cells." (PMID 29138479, 2017). "Interestingly, there is a better overall survival of advanced melanoma patients with high LRP1 expression in monocytes." (PMID 37020553, 2023). "In the context of melanoma, LRP1 has been shown to regulate the metastatic behaviour of melanoma." (PMID 36678596, 2023). "Here we extend our initial studies on the importance of LRP1 for melanoma cell proliferation." (PMID 36612285, 2022). "However, the exact mechanism of how LRP1 expression is regulated in melanoma cells remains undetermined." (PMID 36612285, 2022). "Several studies indicate that LRP1 controls melanoma cell growth." (PMID 36612285, 2022). "In turn, miR-107, by targeting LRP1 impaired melanoma cell proliferation in vitro and in vivo." (PMID 36612285, 2022). "Ultimately, we identified that knockdown of the LRP1 protein could inhibit proliferation and metastasis of melanoma cells, the same effect produced by transfecting the YAP-sh plasmid into melanoma cells." (PMID 29138479, 2017). "Therefore, we performed an MTT-based assay and a transwell assay and measured caspase-3/7 activity to investigate if LRP1 had an effect on the transformative phenotypes of melanoma cells." (PMID 29138479, 2017). "Our data are consistent with our hypothesis and provide important information that YAP and LRP1 have similar functions in maintaining the transformative phenotypes of melanoma A375 cells and MUM-2B cells." (PMID 29138479, 2017). "Here, we further investigated whether LRP1 was important for the anti-apoptotic role of YAP in melanoma A375 cells and MUM-2B cells." (PMID 29138479, 2017). "However, it was also clarified that LRP1 may play a role as a suppressor receptor for the metastatic phenotype in melanoma in response to ApoE." (PMID 36839884, 2023). "In addition, we observed that YO-2 treatment downregulated LRP1 in melanoma cells." (PMID 36612285, 2022). "However, the mechanism of LRP1 expression in melanoma cells remains only partially understood." (PMID 36612285, 2022). "Furthermore, tPA, in part via LRP1, enhanced lung metastasis in the B16 melanoma model." (PMID 33669052, 2021). "The chemosensitivity of melanoma cells could be improved when tPA or LRP1 was knocked down." (PMID 33669052, 2021). "In addition, reduction of YAP-impaired pro-carcinogenic phenotypes could be partially reversed by simultaneous overexpression of LRP1, suggesting that LRP1 is functionally important in YAP-induced melanoma tumorigenesis." (PMID 29138479, 2017). "In the pathogenesis of melanoma tumorigenesis, LRP1 may be a crucial protein." (PMID 29138479, 2017). "However, whether and how LRP1 and YAP are closely associated with each other in melanoma cells is poorly understood." (PMID 29138479, 2017).
melanoma (continued). "The interaction between LRP1 and PAI-1 can promote the endocytosis of PD-L1 on the surface of melanoma cell membrane and enhance immune escape." (PMID 36605486, 2023). "The human skin carcinoma and melanoma cells A431 and SK-MEL-28 or the murine B16F1 and B16F10 (high and low metastatic potential) showed impaired LRP1 expression compared to fibroblast/stromal cell controls (HS-5 and murine MEF1 cells)." (PMID 36612285, 2022). "YO-2 dose-dependently decreased LRP1 expression in A431 and B16F10 cells, suggesting that YO-2 impairs LRP1 expression in melanoma cells." (PMID 36612285, 2022). "Restoration of LRP1 in the less aggressive, poorly metastatic B16F1 tumor cells enhanced tumor cell proliferation and led to lung metastasis in murine melanoma models." (PMID 36612285, 2022). "We further compared the relative gene expression ratios of target genes LRP1, ACTB and GAPDH across 13 melanoma cell lines estimated by qRT-PCR or ddPCR." (PMID 31567589, 2020). "By testing a series of melanoma and normal skin tissues on TMA slides using IHC, we found that both YAP and LRP1 levels were highly elevated in melanoma tissues compared to normal skin tissues." (PMID 29138479, 2017). "This study is also the first experiment to reveal the role of LRP1 in the mechanism of melanoma tumorigenesis and to explore the relationship between YAP and LRP1." (PMID 29138479, 2017). "Therefore, we concluded that the carcinogenic function of YAP may rely on LRP1 in melanoma cells." (PMID 29138479, 2017). "YO-2 treatment reduced melanoma proliferation in Mock and LRP1 OE expressing, but not LRP1 KD cells in vitro, and tumor growth in Mock and LRP1-OE tumors in vivo." (PMID 36612285, 2022). "By comparing the relative expression ratios of target genes LRP1, ACTB and GAPDH across two melanoma cell lines estimated using an RNAseq approach and a qRT-PCR-based approach, we show that indeed we obtain similar relative gene expression levels of the target genes." (PMID 31567589, 2020). "Taken together, our results suggest that YAP regulates LRP1 through stimulation of the LRP1 promoter and that LRP1 may be an important target for influencing YAP in melanoma." (PMID 29138479, 2017). "Third, due to the limited number of melanoma patients in China, we did not validate the relationship between YAP and LRP1 proteins in melanoma samples that included blood and cutaneous tissues." (PMID 29138479, 2017). "In the present study, we have identified a significant new target, LRP1, which may be important in YAP-induced melanoma tumorigenesis." (PMID 29138479, 2017). "Interestingly, higher expression levels of YAP were correlated with higher expression levels of LRP1 in melanoma tissues, suggesting the importance of the collaboration between YAP and LRP1 in clinical melanoma samples." (PMID 29138479, 2017). "Therefore, PCSK9 is capable of mediating the degradation of LRP-1 in both human HEK293 and HepG2 cells, as well as in mouse B16 melanoma cells." (PMID 23675525, 2013).
melanoma (continued). "The observation presented here that LRP-1 protein levels could also be regulated by PCSK9 is significant, since PCSK9 was recently shown to modulate the metastatic potential of melanoma cells and LRP-1 is a well-known factor involved in tumour metastasis." (PMID 23675525, 2013). "This led us to identify the low density lipoprotein receptor-related protein 1 (LRP-1) as a receptor whose degradation is induced by PCSK9 in two melanoma cell lines, in which we previously showed that the lack of host mouse PCSK9 reduced their metastasis in liver." (PMID 23675525, 2013). "To investigate whether LRP1 is co-localized with YAP in melanoma A375 cells and MUM-2B cells, we performed IF analysis with anti-YAP and anti-LRP1 antibodies and found that YAP was not co-localized with LRP1." (PMID 29138479, 2017).